FSTL1 (follistatin like 1)
Description:
Secreted glycoprotein that is involved in various physiological processes, such as angiogenesis, regulation of the immune response, cell proliferation and differentiation. Plays a role in the development of the central nervous system, skeletal system, lungs, and ureter (By similarity). Promotes endothelial cell survival, migration and differentiation into network structures in an AKT-dependent manner. Also promotes survival of cardiac myocytes (By similarity). Initiates various signaling cascades by activating different receptors on the cell surface such as DIP2A, TLR4 or BMP receptors.
Synonyms: FRP; FSL1; OCC1; OCC-1; tsc36
Tractability: Antibody: UniProt places it where antibodies can reach, with high confidence; its Gene Ontology location is reachable by antibodies, with high confidence; UniProt predicts a signal peptide or a membrane-spanning region. PROTAC: ubiquitination databases record sites on it; its protein half-life has been measured.
Gene: Protein-coding gene on chromosome 3 (120,392,293 to 120,451,241, reverse strand). Ensembl gene ENSG00000163430.
Subcellular location: Secreted
Subcellular location (Human Protein Atlas): Vesicles; Cytosol; Golgi apparatus; Predicted to be secreted
Pathways (Reactome):
Metabolism of proteins: Post-translational protein phosphorylation; Regulation of Insulin-like Growth Factor (IGF) transport and uptake by Insulin-like Growth Factor Binding Proteins (IGFBPs)
Signal Transduction: Signaling by BMP
Gene Ontology:
Molecular function: protein binding; heparin binding; calcium ion binding
Biological process: cell differentiation; endothelial cell differentiation; endothelial cell migration; negative regulation of apoptotic process; regulation of BMP signaling pathway
Cellular component: extracellular exosome; extracellular region; endoplasmic reticulum lumen
Genetic constraint (gnomAD): Loss-of-function variants: 8 observed, 17.92 expected, observed/expected ratio (o/e) 0.45, 90% interval 0.26 to 0.81. The upper end of that interval is the gene's LOEUF score, 0.81, which puts it in group 3 of 6, group 1 being the genes least tolerant of losing a copy. Missense variants: 164 observed, 182.3 expected, observed/expected ratio (o/e) 0.9, 90% interval 0.79 to 1.02. Synonymous variants: 64 observed, 63.96 expected, observed/expected ratio (o/e) 1, 90% interval 0.82 to 1.23.
Homologues: Orthologues: chimpanzee FSTL1 (99% identical), pig FSTL1 (98% identical), dog FSTL1 (96% identical), macaque FSTL1 (95% identical), rabbit FSTL1 (95% identical), mouse Fstl1 (92% identical), guinea pig FSTL1 (90% identical), rat Fstl1 (88% identical), zebrafish fstl1b (71% identical), tropical clawed frog fstl1 (71% identical), zebrafish fstl1a (67% identical). Paralogues in human: FSTL4 (31% identical), FSTL5 (29% identical), SPINK5 (17% identical), FST (14% identical), FSTL3 (12% identical), SPINK6 (4% identical).
Diseases named in the same sentence as FSTL1 in open-access papers:
FSTL1 is named in the same sentence as 198 diseases in open-access papers, as found by Europe PMC text mining. Sharing a sentence is not in itself a finding about the gene and the disease. The quoted sentences say what the papers report.
myocardial infarction (29 papers, 2014 to 2026). Gross necrosis of the myocardium, as a result of interruption of the blood supply to the area, as in coronary thrombosis. "Follistatin-like protein 1 (FSTL1) has been found to protect cardiac fibroblasts from injury induced by diabetes mellitus-associated myocardial infarction (DM-MI)." (PMID 38322269, 2024). "Administration of Fstl1 protein significantly attenuated I/R-induced myocardial infarct areas associated with reduced apoptosis and decreased detrimental immune responses." (PMID 27799944, 2016). "In the repair process following myocardial infarction, FSTL1 promotes the transformation of cardiac fibroblasts into myofibroblasts, enhancing ECM deposition, particularly increasing collagen and fibronectin in the myocardial interstitium." (PMID 41602834, 2026). "Under hypoxic conditions (such as after myocardial infarction), the secretion of FSTL1 by human cardiac fibroblasts increases, and the low-glycosylated form of FSTL1 promotes better regenerative effects, particularly in enhancing cell proliferation." (PMID 41602834, 2026). "In an animal model, FSTL1 is upregulated in the heart after myocardial infarction and ischaemia/reperfusion injury and protects cardiac myocytes against hypoxia/reoxygenation-induced apoptosis in a manner that is dependent on Akt and ERK19." (PMID 41198895, 2025). "Recently, in an animal model of myocardial infarction, researchers reported that FSTL1 is a molecular link between 4 weeks of training and training-derived cardiovascular benefits." (PMID 41198895, 2025). "Animal experiments revealed that exercise-induced follistatin-like protein 1 (FSTL1) improve cardiac function after myocardial infarction through a comprehensive protective effect of inhibiting apoptosis, reducing fibrosis and promoting angiogenesis." (PMID 40917801, 2025). "FSTL1, which we observed more highly expressed in CFs-Clathrin pathways, is expressed after myocardial infarction by CFs and myofibroblasts and is crucial during initial cardiac repair." (PMID 41030476, 2025). "In a rat model of myocardial infarction, the blood FSTL1 level and FSTL1 expression in cardiac and skeletal muscles increase after aerobic training." (PMID 41198895, 2025). "Interval aerobic exercise training (treadmill running, alternated between 7 min at 25 m/min and 3 min at 15 m/min)‐induced increase in myocardial FSTL1 expression attenuates cardiac dysfunction in a rat model of myocardial infarction." (PMID 35585770, 2022). "FSTL1 protected the heart against I/R (ischemia-reperfusion) injury by reducing myocardial infarct size and improved cardiomyocyte survival by increasing the phosphorylation of Akt and ERK signaling." (PMID 34957094, 2021). "Acute myocardial infarction (MI) model was created by ligating the left anterior descending coronary artery, while control MSCs (MSCs-mCherry) or Fstl1-overexpressing MSCs (MSCs-Fstl1) were injected into the peri-infarct zone simultaneously." (PMID 30635025, 2019). "In conclusion, our current data demonstrated a favorable role of Fstl1 in stem cell-based therapy for experimental myocardial infarction." (PMID 30635025, 2019). "It was shown that Fstl1 is a cardiokine upregulated by various heart stresses, including cardiac ischemia/reperfusion injury, pressure overload, and myocardial infarction." (PMID 31034503, 2019). "Curiously, epicardial FSTL1 declines following myocardial infarction but application of human FSTL1 via an epicardial patch was able to stimulate cardiomyocyte proliferation, to improve cardiac function and survival, in mouse and swine MI models." (PMID 28979901, 2016). "After an MI (myocardial infarction), several genes and factors are (re)activated that affect myocardial damage, such as epicardium-derived follistatin-like-1 and mineralocorticoid receptor expressed by VSMCs." (PMID 29367572, 2016). "Follistatin‐like 1 (Fstl1) is a secreted protein that is acutely induced in heart following myocardial infarction (MI)." (PMID 27234440, 2016).
myocardial infarction (continued). "FSTL1 is a cardiokine, whose cardiac expression levels are upregulated in hypertrophic hearts of mice or in myocardial infarction models." (PMID 25171167, 2014). "Multiple studies show that FSTL1 is induced after ischemia–reperfusion or myocardial infarction, and giving exogenous FSTL1 in animal I/R models can reduce infarct size and lessen injury—suggesting it may be protective early in the acute damage phase." (PMID 41602834, 2026). "All this strongly suggests that regulation of FSTL1 expression and glycosylation after myocardial infarction could guide approaches on exploiting its regenerative potential for the heart." (PMID 35317048, 2022). "Another investigation found that administration of human FSTL1 protein significantly attenuated myocardial infarct size in a mouse and a pig model of ischemia/reperfusion, which was associated with diminished apoptosis and inflammatory responses in the ischemic heart." (PMID 36290379, 2022). "On the other hand, in myocardial infarction model rats, intermittent aerobic exercise training increases circulating FSTL1 levels and concomitantly increases the expression levels of skeletal muscle and myocardial FSTL1 protein." (PMID 35585770, 2022). "Similarly, in our study, using an in vivo model of myocardial infarction in mice, we detected a strong upregulation of FSTL1 in epicardial cells undergoing EMT during acute MI." (PMID 34067060, 2021). "Furthermore, Fstl1 is disappears from epicardial cells in the mouse heart with myocardial infarction." (PMID 31034503, 2019). "Moreover, data indicate that FSTL-1 is upregulated after myocardial infarction and prevents cardiac rupture by activating cardiac fibroblasts." (PMID 29695980, 2018). "Follistatin-like 1 (FSTL1) is an emerging multifunctional glycoprotein that plays a central role in cardiac repair following myocardial infarction (MI)." (PMID 41602834, 2026). "As an in vivo use case of our system, we investigated the functional effect of multi-dose regimens of human follistatin-like 1 protein (FSTL1) in a rat model of myocardial infarction (MI)." (PMID 41740294, 2026). "Additionally, an increase in secretion of FSTL1 with higher molecular weight, likely due to protein glycosylation, could be observed in mouse serum and myocardium after myocardial infarction." (PMID 35317048, 2022). "FSTL1 expression is regulated by a variety of physiological and systemic factors, including age, sex, adiposity, and immune interactions, which can influence its cardioprotective effects, particularly after myocardial infarction (MI)." (PMID 41602834, 2026). "Finally, implantation of recombinant human Fstl1 via epicardial cell patch stimulated cell-cycle entry and promoted the division of preexisting cardiomyocytes, attenuating cardiac dysfunction and improving survival in mouse and porcine myocardial infarction models." (PMID 27799944, 2016). "However, administration of FSTL1 reduced ischemic damage and inflammatory response with AMP-activated protein kinase- and bone morphogenetic protein-4-dependent mechanisms in a myocardial infarction model." (PMID 31952198, 2020). "It has been reported that FSTL-1 is secreted by skeletal myocytes, myocardial tissue after myocardial infarction, and cardiomyocytes and nonmyocytes." (PMID 29695980, 2018). "In the myocardial infarction (MI) model a significant increase in Fstl1 expression at one and two weeks after MI was found when normalizing the data with the validated reference genes Eef1e1 and Rpl4 (F = 6.348, p = 0.011)." (PMID 28154421, 2017).
Obesity (23 papers, 2013 to 2026). Accumulation of substantial excess body fat. "This study aimed to evaluate the outcomes of BS in a cohort of 48 Uruguayan patients and investigate the interplay between BS and clinical and metabolic features, with a specific focus on FSTL1, an emerging biomarker associated with obesity and inflammation." (PMID 38956222, 2024). "A decrease in FSTL1 expression is associated with a reduction in adipogenesis in severe obesity, which is accompanied more severe senescence in preadipocytes and increased apoptosis in adipocytes, which conflicts with previous results." (PMID 37667400, 2023). "Another possible reason for the FSTL1 decrease in morbidly and super obese is that obesity is associated with the increase of senescent cells in adipose tissue." (PMID 30595761, 2018). "It was later observed that FSTL1 encodes a preadipocyte/adipocyte-secreted protein with a possible implication in obesity inflammation." (PMID 30595761, 2018). "In this study, we investigated the association of FSTL1 with obesity and its actions on adipocytes and macrophages." (PMID 24347831, 2013). "FSTL1 is a glycoprotein primarily produced by mesenchymal cells linked to various pathologies, including cardiovascular, autoimmune, neoplastic, osteoarticular conditions, and obesity (reviewed in11)." (PMID 38956222, 2024). "Indeed, a recent study found that FSTL1 deficiency inhibited preadipocyte differentiation in vitro and obesity development in vivo." (PMID 35909571, 2022). "In conclusion, it is biologically possible that overweight and mild obesity are associated with increased FSTL1 levels predominantly due to its proinflammatory action during this chronic low-grade inflammation state and a higher number of preadipocytes which willingly express FSTL1." (PMID 30595761, 2018). "We identified several associations of the FSTL1 protein level or its genetic variant with obesity." (PMID 30595761, 2018). "In addition, respiratory quotient is the only obesity-related trait which was associated with a genetic variant within the FSTL1 gene so far by the means of GWAS." (PMID 30595761, 2018). "Together, FSTL1 is shown to be associated with obesity in humans." (PMID 24347831, 2013). "In the present study, we show that FSTL1 is associated with obesity in both mice and humans." (PMID 24347831, 2013). "To probe the role of FSTL1 in vivo, we then examined its expression levels in subcutaneous and epididymal adipose tissue of ob/ob mice, a well-characterized model of severe genetic obesity and insulin resistance resulting from leptin deficiency." (PMID 24347831, 2013). "In light of the inflammatory induction of FSTL1 in adipocytes and its proinflammatory actions, we hypothesized that FSTL1 may be implicated in adipose tissue inflammation and insulin resistance in obesity." (PMID 24347831, 2013). "However, using transgenic animal models, FSTL1 has been implicated in multiple signaling pathways and its role during diseases like obesity remains unclear." (PMID 39376657, 2024). "Therefore, because of the discrepancy in FSTL1 expression responses to obesity, the difference in genetic background or severity of obesity may be associated with transcriptional and translational regulation of FSTL1 levels." (PMID 35585770, 2022). "Therefore, low FSTL1 expression in other organs may be associated with a reduction in circulating FSTL1 levels in obesity." (PMID 35585770, 2022). "Although some adipokines, including, e.g., leptin, adiponectin, ghrelin, resistin, or interleukins have been studied extensively, the role of many others, including follistatin-like 1 (FSTL1), which has also been suggested as linked to obesity, remains unclear." (PMID 30595761, 2018). "As FSTL1 has been described as functionally implicated in a range of processes including apoptosis, inflammation, or adipogenesis, it is not surprising that some of its functions may play a significant role in the obesity development." (PMID 30595761, 2018).
Obesity (continued). "This research, despite limitations of a small sample size and limited follow-up time, contributes valuable insights into understanding and predicting the success of BS, highlighting the potential role of FSTL1 as a useful biomarker in obesity." (PMID 38956222, 2024). "Other studies have already proposed that FSTL1 plays a role in obesity, although its role in the pathogenesis of the disorder or its presentation has not been fully elucidated yet." (PMID 38956222, 2024). "It has also been shown that FSTL1 plays an active role in the obesity-induced inflammatory response in both mice and humans." (PMID 38956222, 2024). "Our results, therefore, present novel tools to evaluate BS while further supporting the potential use of FSTL1 as a biomarker in obesity." (PMID 38956222, 2024). "More recently, the work by Lee and colleagues sought to analyze the levels of circulating FSTL1 with the presentation of obesity, analyzing a cohort of 230 Korean individuals, comparing participants according to their BMI and metabolic health state." (PMID 38956222, 2024). "Cardiokines such as FSTL1 and miR-22-3p exhibit high pathological levels in obesity and diabetes, leading to an abundant proinflammatory profile including IL-6, TNF-α and MCP-1." (PMID 37667400, 2023). "Serum FSTL1 levels are higher in subjects with overweight, obesity, or T2DM than in healthy lean controls." (PMID 35909571, 2022). "Recent studies have indicated a close relationship between FSTL1 and obesity-induced chronic inflammation and insulin resistance." (PMID 35909571, 2022). "On the other hand, pathological and severe obesity decreased FSTL1 levels due to a continuous increase in the number of matured adipocytes and other associated factors." (PMID 34440203, 2021). "The authors suggested that decreased FSTL1 concentrations observed in people with severe obesity result from a reduction of adipogenesis accompanied by a senescence of preadipocytes, increased adipocyte apoptosis, and epigenetic FSTL1 silencing." (PMID 33192583, 2020). "Once we employed this model, we observed that both obesity status (p = 0.042) and the interaction of obesity status with genotype (p = 0.004) exert significant prediction roles for FSTL1 protein level." (PMID 30595761, 2018). "We located and investigated such SNP (rs1057231) in relation to the FSTL1 protein level, obesity status, and other body composition parameters." (PMID 30595761, 2018). "One of the possible epigenetic regulation resulting in FSTL1 downregulation in obesity is methylation." (PMID 30595761, 2018). "Together, our results suggest a potential role of FSTL1 in adipose tissue inflammation and insulin resistance in obesity." (PMID 24347831, 2013). "Together, our results suggest that FSTL1 is a potential mediator of inflammation and insulin resistance in obesity." (PMID 24347831, 2013). "Additionally, adiposity and obesity-related inflammation modulate FSTL1 expression, with obesity generally leading to altered secretion patterns, although inflammation can upregulate its levels." (PMID 41602834, 2026). "Thus, Fstl1 has the potential to be used as a therapeutic target for treating obesity and improving metabolic health." (PMID 39376657, 2024). "Importantly, the two studies did provide important data supporting the role of FSTL1 as a biomarker in obesity." (PMID 38956222, 2024). "Moreover, these three bacterial strains were significantly associated with certain adipo-myokines related to obesity or inflammation (LIF, FSTL1, FGF21, SPARC, and IL6)." (PMID 39391493, 2024). "Importantly, different studies highlight the potential role of FSTL1 as a biomarker for various conditions, including obesity." (PMID 38956222, 2024). "A possible explanation may be that FSTL1 is exhausted by the significant senescence of the accumulated preadipocytes in extreme obesity, which leads to exacerbated apoptosis in adipocytes." (PMID 37667400, 2023).